ICAM1 (intercellular adhesion molecule 1)
Diseases named in the same sentence as ICAM1 in open-access papers (continued):
Sharing a sentence is not in itself a finding about the gene and the disease.
allergic asthma (7 papers, 2011 to 2025). A asthma with a basis in a pathological type I hypersensitivity reaction. "The current results suggested that CASP3, CCND1, ICAM1, RAF1, and ERBB2 expression are causally related to the risk of allergic asthma." (PMID 39769348, 2024). "The present MR results suggested the presence of associations between the risk of allergic asthma and BAX, CASP3, CCND1, ICAM1, PEBP1, RAF1, and ERBB2 expression." (PMID 39769348, 2024). "Based on the inverse variance weighted method, the MR analysis provided evidence of associations between allergic asthma and BAX, CASP3, CCND1, ERBB2, ICAM1, PEBP1, and RAF1 in the blood." (PMID 39769348, 2024). "We also found that RN markedly suppressed increased ICAM-1 and HO-1 expression in lung tissue of allergic asthma rats." (PMID 20953388, 2011).
angina pectoris (7 papers, 2010 to 2025). The symptom of paroxysmal pain consequent to MYOCARDIAL ISCHEMIA usually of distinctive character, location and radiation. "Bao Xin decoction (another formula to treat PSCS with IHD) was effective in curing CAD with stable angina pectoris and acting by inhibiting serum interleukin 6 (IL-6), intercellular adhesion molecule 1 (ICAM-1) and tumor necrosis factor-α (TNF-α) levels and decreasing inflammatory reactions." (PMID 29403392, 2018). "Regarding ACS, a study that included 75 patients measured circulating levels of ICAM-1 and VCAM-1, VCAM-1 showed to be a powerful predictor of major events in this patient profile; however, a new coronary event, hospitalization for angina, or cardiac death were considered adverse outcomes." (PMID 31778438, 2019). "Elevated plasma levels of ICAM-1 were associated with the risk of AMI, coronary death, and angina during follow-up, an outcome not observed when serum levels of VCAM-1 were assessed." (PMID 31778438, 2019).
B-cell lymphoma (7 papers, 2006 to 2022). "We repeated NK-92 competitive co-culture experiments after disruption of DCAF15, PTPN2, STAT1 and ICAM1 in Daudi cells, a B2M-deficient B-cell lymphoma line." (PMID 31452512, 2019). "Prior to customizing the TaqMan Protein Expression Assay for SH2-PLA (i.e., modular domain binding assay), we tested the performance of the original proximity ligation assay using the kit-supplied anti-ICAM1 assay probes and Raji B-cell lymphoma lysate." (PMID 26112401, 2015). "We then treated with metformin the primary cells from a B-cell lymphoma patient (BCL-P2) and observed that it significantly increased expression of ULBP1 and ICAM-1 and tended to increase MICA/B and CD20 expression." (PMID 35079096, 2022). "Murine A20 B-cell lymphoma cells expressing CD40L have been shown to upregulate CD80, CD86, ICAM-1, Fas and MHC molecules." (PMID 33666760, 2021). "LOAd703 could infect and replicate in B-cell lymphoma cell lines (BC-3, Karpas422, Daudi, DG-75, U-698) and induced an overall enhanced immunogenic profile with upregulation of co-stimulatory molecules CD80, CD86, CD70, MHC molecules, death receptor Fas and adhesion molecule ICAM-1." (PMID 33666760, 2021).
Burkitt lymphoma (7 papers, 2014 to 2022). A rare form of malignant mature B-cell non-Hodgkin lymphoma. "Further, we blocked ICAM-1 and B7-2 on the surface of an EBV-positive Burkitt’s lymphoma cell line, Daudi, which has been shown previously to enhance T-cell activation in response to increased ICAM-1 and B7-2 surface levels." (PMID 33411730, 2021). "RT-qPCR and Western blot analysis showed that the AF1q expression at both the mRNA and protein levels reciprocally regulated the expression of ICAM-1 in Burkitt’s lymphoma cell lines." (PMID 31297450, 2019). "It is well known that downregulation of ICAM-1 in Burkitt’s lymphoma enhances the probability of escape of tumor cells from T cell surveillance." (PMID 31297450, 2019). "In summary, CDK4/6 inhibitors are shown here to inhibit proliferation of PEL, KSHV-infected endothelial cells, and EBV+ Burkitt’s lymphoma cells and also to reverse virus-induced suppression of MHC-I, ICAM-1, and B7-2 on these cells." (PMID 35562811, 2022).
carotid atherosclerosis (7 papers, 2016 to 2021). A thickening and loss of elasticity of the walls of carotid arteries that occur with formation of atherosclerotic plaques. "In our study, the EE genotype of the rs5498 of the ICAM-1 gene was associated with a more rapid progression of carotid atherosclerosis in subjects with T2DM in comparison with other genotypes." (PMID 27090396, 2016). "The purpose of the study was to investigate an association between the rs5498 polymorphism of the ICAM-1 gene and the progression of carotid atherosclerosis in patients with T2DM." (PMID 27090396, 2016). "An association between the rs5498 polymorphism of the ICAM-1 gene and the progression of carotid atherosclerosis in subjects with T2DM was demonstrated in the present study." (PMID 27090396, 2016). "The EE genotype of the rs5498 of the ICAM-1 gene was associated with a more rapid progression of carotid atherosclerosis in patients with T2DM in comparison with other genotypes." (PMID 27090396, 2016). "It has also been demonstrated to be related to carotid atherosclerosis, arterial wave reflection, and intercellular adhesion molecule-1 levels." (PMID 32574194, 2020). "Fibrinogen levels were positively associated with CCA-IMT while ICAM-1, CCL2, and sTNF-αR1 were positively associated with bifurcation-IMT, our secondary measures of subclinical carotid atherosclerosis." (PMID 30946765, 2019).
coronary atherosclerosis (7 papers, 2010 to 2023). Atherosclerosis of the coronary vasculature. "Tang and co-workers reported that the level of serum ICAM-1 was associated with calcium score as a marker of coronary atherosclerosis." (PMID 27090396, 2016). "In this case-control study, we found the association between polymorphisms of ICAM-1 and coronary atherosclerosis patients with coronary stenosis." (PMID 25310099, 2014). "In the statistical analysis of ICAM-1 gene polymorphisms and coronary atherosclerosis, we found the statistical difference (P<0.05) in the genotypes, haplotypes and risk factors." (PMID 25310099, 2014). "Relationship between ICAM-1 polymorphisms and risk factor of coronary atherosclerosis in coronary stenosis patients." (PMID 25310099, 2014). "We found that there were four haplotypes that had a frequency of more than 5%, in ICAM-1 polymorphisms among the coronary atherosclerosis case and control groups." (PMID 25310099, 2014). "But only few of the results had significant difference (P<0.01), so the further analyis of ICAM-1 gene polymorphisms and coronary atherosclerosis should focus on more samples and statistical analysis." (PMID 25310099, 2014). "Haplotypes of ICAM-1 gene and risk of coronary atherosclerosis." (PMID 25310099, 2014). "The association between polymorphisms of ICAM-1 gene and coronary atherosclerosis." (PMID 25310099, 2014). "We explored the association between the polymorphisms of the ICAM-1 gene and coronary atherosclerotic stenosis to determine whether any risk factors correlate with genetic polymorphisms in Chinese patients with coronary atherosclerosis." (PMID 25310099, 2014). "Thus ICAM-1 might be associated with the pathology of coronary atherosclerosis, especially the soluble conformation." (PMID 25310099, 2014). "Thus ICAM-1 genetic variations may be a relevant influencing factor when considering the risk factors of coronary atherosclerosis." (PMID 25310099, 2014). "Current research on the relationship between the genetic variations in the ICAM-1 gene and coronary atherosclerosis is increasingly relevant." (PMID 25310099, 2014).
meningitis (7 papers, 2011 to 2024). A disorder characterized by acute inflammation of the meninges of the brain and/or spinal cord. "Our findings strongly support the functional involvement of PDGF-BB and ICAM-1 in meningitic E. coli invasion of the BBB, which represent important targets for further prevention and therapy of CNS disorders resulting from meningitis-causing pathogens." (PMID 31092253, 2019). "Proinflammatory cytokines (IL-1β, IL-6, TNFα, MCP-1, MIP-1alpha, and RANTES) and adhesion molecules (CD44 and ICAM-1) were significantly reduced in the cerebrospinal fluids of the α7-/- mice with E. coli meningitis." (PMID 21966399, 2011). "PDGF-BB, as well as ICAM-1, are therefore likely to represent important candidate targets, which may provide novel insights for future prevention and non-antibiotic therapy for pathogenic E. coli meningitis." (PMID 31092253, 2019). "The release of P65 and the adhesion molecules ICAM-1 and CD44 into CSF were all augmented by E44 infection and suppressed by both vimentin deficiency and IbeA deletion, which confirmed IbeA-vimentin interaction could aggravate the inflammatory response in E. coli meningitis." (PMID 27657497, 2016). "These are knowingly associated with neuroinflammation, compromising BBB integrity and favoring leukocyte transmigration, such as seen in meningitis and in autoimmune encephalomyelitis; in endothelial progenitor cells in vitro, NF-kB activation is known to induce expression of both VCAM-1 and ICAM-1." (PMID 36361571, 2022).
neuropathy (7 papers, 2020 to 2025). A disorder affecting the nervous system that manifests with pain, tingling, numbness, and/or muscle weakness. "After the onset of clinical signs of neuropathy, ICAM1-deficient NOD mice were assigned to treatment twice per week with anti-FcRn antibody, isotype control antibody (negative control) or intraperitoneal (administered) immunoglobulin (positive control)." (PMID 39674966, 2024).
pouchitis (7 papers, 2012 to 2022). Acute inflammation in the intestinal mucosa of the continent ileal reservoir (or pouch) in patients who have undergone ileostomy and restorative proctocolectomy (proctocolectomy, restorative). "Alicaforsen, which treats pouchitis and left-sided UC by inhibiting ICAM-1 production, has been granted orphan drug designation and is available as an unlicensed drug under international regulations." (PMID 35719390, 2022). "Intercellular adhesion molecule-1 (ICAM-1), is a cell surface receptor that directs the white blood cells in circulation to sites of inflammation and increases the inflammatory response in pouchitis." (PMID 32604776, 2020). "ICAM1 was selected as a target for IBD because of its role in cell trafficking, because it is present during intestinal inflammation and because increasing levels of circulating protein are observed in patients with CD, UC and pouchitis." (PMID 22989709, 2012).
renal carcinoma (7 papers, 1994 to 2025). A carcinoma arising from the epithelium of the renal parenchyma or the renal pelvis. "A recent study revealed that RARRES1 exerts an anti-tumor effect by promoting ICAM1 expression and inducing M1 macrophage activation in renal cancer in vitro." (PMID 38533207, 2024). "The molecular mechanisms of GJH action involve the downregulation of chemotherapeutic agent resistance-related genes and ICAM-1 expression, in parallel with the reduction of NF-κB expression and activation in 786-O renal carcinoma cells." (PMID 22028734, 2012). "Our study shows that SIGIRR downregulation in RCC cells unleashes an inflammatory signaling intrinsic to renal cancer cells that leads to NFKBIZ activation, IL6 induction, MMP1 upregulation, and notably higher levels of PD-L1 and ICAM1 expression." (PMID 35814450, 2022).
renal cell carcinoma (7 papers, 2001 to 2024). "Other studies showed an association between ICAM-1 expression and infiltration of lymphocytes into tumor tissue of patients with renal cell carcinoma, colorectal and esophageal cancer." (PMID 26513172, 2015). "CCL22, CRP, ICAM1, IFNG, PDGFRA, TGFB1 and TNFSF11 have been confirmed to be involved in the malignant progression and metastasis of renal cell carcinoma through different biological mechanisms." (PMID 34187413, 2021). "For instance, in renal cell carcinoma, CCN3 promotes cell migration and invasion by upregulating ICAM-1 and COX-2 expression." (PMID 29088803, 2017). "Two renal cell carcinoma cell lines (49RC 43STR and 75RC 2STR) were characterized by detection of the cell surface proteins: CD44(var), intercellular adhesion molecule-1 (ICAM-1), urokinase-type plasminogen activator (uPA) and its receptor and aminopeptidase N (APN)." (PMID 11556847, 2001).
rhinitis (7 papers, 2018 to 2026). An inflammation of the mucous membrane lining the nose, usually associated with nasal discharge. "We observed a significant reduction in VCAM-1 and ICAM-1 levels in patients with moderate-to-severe forms, compared with patients with mild rhinitis (p = 0.03, p = 0.01, respectively)." (PMID 35011854, 2021). "Finally, the clever intranasal application of antibodies bispecific for allergens and Intercellular Adhesion Molecule 1 (ICAM-1) as a topical treatment for allergic and RV-induced rhinitis is explained." (PMID 35387044, 2021). "Persistent low-grade inflammation (ICAM-1/CD54 expression) has been detected in the conjunctival and nasal epithelium of rhinitis during asymptomatic periods." (PMID 36747108, 2023). "In the present study, we also noticed a significant reduction of CAM levels in patients with moderate-severe forms compared to patients with mild rhinitis (VCAM-1 p = 0.037, ICAM-1 p = 0.001 and E-selectin p = 0.002)." (PMID 30008985, 2018). "The clinical (rhinitis symptoms and total symptoms score (TSS), type of sensitization) and biological evaluation (total IgE, eosinophils, ICAM-1, VCAM-1, and E-selectin) as well as fractionate nitric oxide in exhaled air (FeNO) measurement was performed before and after treatment." (PMID 30008985, 2018). "Secondary outcomes include Total Non-nasal Symptom Score (TNNSS), Rhinitis Quality of Life Questionnaire (RQLQ), serum chemokine Eotaxin, Inter Cellular Adhesion Molecule-1 (ICAM-1), and Eosinophil Cationic Protein (ECP)." (PMID 41907282, 2026).
steatosis (7 papers, 2012 to 2024). Increased lipid within the cytoplasm of cells. "Prior to transplantation, ethanol treatment causes steatosis and upregulation of ICAM-1 expression in donor wild type livers." (PMID 22778492, 2012). "Consequently, we also demonstrated that higher levels of ICAM-1 corresponded to worsening severity of steatosis, which underscores the escalating cardiovascular risk in these patients at the end of the spectrum of the disease." (PMID 34191823, 2021). "Steatosis was associated with increased hepatic ICAM-1 expression." (PMID 22778492, 2012). "The degree of steatosis in patients with NAFLD was significantly correlated with severity of OSA, CIMT measurements, ICAM-1 and Lp(a)." (PMID 34191823, 2021). "By contrast in mice fed EtOH+Chol, ALT increased to ~270 U/L, steatosis was more extensive and mostly macrovesicular, and expression of proinflammatory molecules (HMGB-1, TLR4, TNFα, ICAM-1) and leukocyte infiltration increased substantially." (PMID 27676640, 2016). "It has been reported that KCs upregulate ICAM-1 to attract more neutrophils into the liver; indeed, the serum ICAM-1 level was significantly higher in the patients with MASH than in the patients with simple steatosis and in the normal subjects." (PMID 38612483, 2024). "Expression of IL-8 and ICAM-1 is dependent on c-Jun N-terminal kinase (JNK) activity, and increased JNK activation has also been identified as critical pathological factor in the progression from steatosis to inflammation in NAFLD." (PMID 28055957, 2017). "Overall, although ICAM-1 upregulation did not occur in ICAM-1 deficient mice, hepatic histology, steatosis, and ALT release were comparable in wild type and ICAM-1 deficient mice after acute ethanol treatment." (PMID 22778492, 2012).
anaplastic thyroid cancer (6 papers, 2017 to 2025). "SSTR2 was used for tracking intercellular adhesion molecule-1 (ICAM-1) CAR T cells in mice bearing anaplastic thyroid cancer with 68Ga-DOTA-D-Phel-Tyr3-Octreotide ([68Ga]68Ga-DOTATOC; DOTA: 1,4,7,10-tetraazacyclododecane-N,N′,N′′,N′-tetra-acetic acid)." (PMID 33042849, 2020). "Furthermore, adoptive cellular therapy using chimeric antigen receptor (CAR) T cells targeting ICAM1 could effectively eliminate patient-derived anaplastic thyroid cancer cells which were overexpressing ICAM1 on their membrane in animal models." (PMID 34408980, 2021). "Furthermore, adoptive transfer of ICAM-1 CAR T cells has been proven safe and feasible in a recent Phase I clinical trial for patients with relapsed/refractory poorly differentiated and anaplastic thyroid cancers." (PMID 40847369, 2025).
aneurysm (6 papers, 2013 to 2024). Bulging or ballooning in an area of an artery secondary to arterial wall weakening. "Significantly, inflammatory-related markers, such as MMP-9 and ICAM1, exhibited prominent staining within smooth muscle layer of fusiform aneurysm lesions, whereas their expression was scarce in cerebral arteries." (PMID 38741091, 2024). "Reported in many research studies, intercellular cell adhesion molecule‐1 (ICAM‐1) plays an important role in aneurysm formation and rupture." (PMID 36879365, 2023). "To validate the SMC phenotype modulation hypothesis, we performed multicolor immunofluorescent staining (mIF) to examine marker proteins associated with phenotypic modulation (including α-SMA, MMP-9 and ICAM1) in fusiform aneurysm and cerebral arteries." (PMID 38741091, 2024). "Similarly, nanocarriers targeting ICAM-1 can reduce leukocyte infiltration in the vascular wall, which is essential in controlling the inflammatory processes that contribute to aneurysm expansion." (PMID 39595942, 2024). "In addition to VCAM-1 and P-selectin, other adhesion molecules such as E-selectin, MCP-1, and ICAM-1 are also expressed at the aneurysm site, further promoting leukocyte infiltration and contributing to local inflammation and tissue remodeling." (PMID 39595942, 2024). "Significant increase of LDL, cholesterol, triglycerides and circulating inflammatory cells was observed in the Ang II-treated animals, and gene expression studies showed that ICAM-1, VCAM-1, MCP-1, M-CSF, MMP-2, MMP-9 and MMP-12 were upregulated in the aorta of aneurysm-induced mice." (PMID 23826202, 2013).
brain inflammation (6 papers, 2017 to 2023). "ICAM1 is involved in the adhesion and transmigration of leukocytes across the endothelium, promoting brain inflammation and resulting in brain diseases." (PMID 29686831, 2018). "A previous study suggested that VCAM-1 and ICAM-1 contribute differently to leukocyte action during brain inflammation, because the expression of adhesion molecules differs depending on tissue type." (PMID 28671640, 2017). "Therefore, the role of VCAM-1 may be more important than that of ICAM-1 in inflammatory brain diseases such as MS." (PMID 28671640, 2017). "Interestingly, increased concentrations of the cell adhesion molecule ICAM-1 in the blood of SARS-CoV-2 infected patients could participate in leukocyte recruitment and exacerbate brain inflammation." (PMID 34386007, 2021).
brain tumors (6 papers, 2015 to 2021). "Our data suggest that increased IFNγ secretion from expanded NK cells can mediate ICAM-1 upregulation and enhanced NK cell conjugate formation in brain tumors and NB, enhancing NK cell activity in adoptive immunotherapy." (PMID 28428785, 2017). "Expression of some cell adhesion molecules, such as ICAM-1 and LFA-3, is dysregulated in GBM compared with normal brain tissue and can serve as a novel marker for brain tumor detection and perhaps therapy." (PMID 28978068, 2017). "In vitro culturing in serum-containing medium has been shown to change the immunological phenotype of brain tumour cells, including upregulation of MHC class I and ICAM-1, and altered cytokine secretion." (PMID 26183281, 2015).